BRAF (B-Raf proto-oncogene, serine/threonine kinase)
Diseases named in the same sentence as BRAF in open-access papers (continued):
Sharing a sentence is not in itself a finding about the gene and the disease.
tumor (continued). "In addition, the UV-low cluster remained an independent prognostic factor in multivariate analysis, together with traditional prognostic factors, such as age, tumor stage, and mutational type (BRAF hotspot or not)." (PMID 36246650, 2022). "Interestingly, BRAF V600E was also identified in this tumor sample." (PMID 34922552, 2021). "Besides, the result of in vivo experiment demonstrated that the restoration of AIM2 expression could inhibit the tumor progression of BRAF-mutant CRC, including tumor growth and distant metastasis." (PMID 33842454, 2021). "Finally, we addressed the role of tumor etiology in PTCs with the same BRAF status." (PMID 34885148, 2021). "In addition, since BRAF inhibitor alone can cause tumor resistance, the combination of BRAF inhibitor with inhibitor targeting MEK, a downstream of BRAF, may be a promising treatment regimen that can avoid the development of drug resistance." (PMID 34568049, 2021). "Future research involving the use of 18F-FDG-PET/CT imaging may investigate the effect of reduction in hypermetabolic tumor mass (by using molecular-targeted therapy [BRAF-/MEK-inhibitors], radiation therapy, and/or surgery) prior to the initiation of treatment with ICI therapy on outcome." (PMID 33418936, 2021). "Furthermore, one variant in EGFR, two in KRAS, and one in BRAF were detected in plasma but not in tumor samples." (PMID 34217228, 2021). "However, mutations in oncogenic drivers such as EGFR, ALK, BRAF, or MET modify the immune tumor microenvironment and may promote anti-PD1/PD-L1 resistance." (PMID 34208111, 2021). "Molecular study: Molecular analysis of the tumor tissue was first performed by Indiana University Molecular Pathology Laboratory and showed that the tumor was microsatellite stable with no mutation in BRAF, KRAS, and NRAS genes." (PMID 34940081, 2021). "Notably, BRAF V600E mCRCs occurred more frequently in female and elderly patients, arising mainly from the right colon and being associated with high tumor burden (involving multiple rather than single metastatic sites) and with high differentiation grading." (PMID 33925278, 2021). "It has been demonstrated that BRAF (V600E) can be acquired as a secondary change during tumor progression or it might be limited to subclonal populations or separate foci in a multifocal tumor." (PMID 34475951, 2021). "In particular, in PTC patients, coexisting BRAF V600E and TERT promoter mutations are associated with increased cancer aggressiveness, lymph node and distant metastases, and an advanced stage and increase tumor recurrence and mortality more rapidly than either alone." (PMID 34208345, 2021). "Therefore, Ocoxin may constitute an effective coadjuvant agent for targeted therapy by directly acting upon metastasis tumor cells and by increasing BRAF inhibitors’ cytotoxicity while impairing tumor microenvironmental support." (PMID 33669949, 2021). "Conversely, the index nodule may harbor the BRAF mutation but does not happen to shed significant BRAF (V600E) DNA due to biological factors including tumor size, invasion, and nodal metastases resulting in negative ctDNA levels." (PMID 34475951, 2021). "However, the cumulative risk of LNM was not statistically significant when calculated by tumor diameter in combination with either BMI, extracapsular invasion, HT or BRAF gene mutation." (PMID 34660255, 2021). "Additionally, BRAF inhibition has been shown to induce RAS mutations in PTC in-vitro studies and has been hypothesized as a tumor escape mechanism." (PMID 34335481, 2021).
tumor (continued). "Consistently, newer data using specific kinase inhibitors for the MEK5/ERK5 pathway, as well as siRNA depletion experiments, demonstrated that tumor cells with oncogenic KRAS or BRAF mutations or ERK5 amplification were not addicted to ERK5 activity for proliferation." (PMID 34299213, 2021). "However, it has been reported that BRAF/MEKi therapy might also affect the tumor microenvironment (TME) and improve durable tumor surveillance, thus having a long-term beneficial effect." (PMID 34065877, 2021). "Furthermore, it has been shown that overexpression of AIM2 could inhibit tumor growth of CRC with BRAF-mutant in vivo." (PMID 33842454, 2021). "Treatment of BRAF-mutated NECs with the BRAF inhibitor dabrafenib and the MEK inhibitor trametinib prevented tumor growth in a xenograft model and also have been reported in single-case reports of patients with metastatic NECs to cause an objective tumor response." (PMID 33807122, 2021). "Interestingly, combining inhibitors of MEK and mutant BRAF kinase delays MAPK-driven acquired resistance and prolongs the duration of responses, achieving higher rate of tumor responses and decreases associated toxicities derived from the paradoxical MAPK pathway activation." (PMID 33672955, 2021). "Several studies suggested that CIMP-positive tumors can lead to a poor overall survival prognosis, and show a close correlation with clinicopathological and molecular characteristics, including tumor location, gender, and whether there are KRAS and BRAF mutations." (PMID 34321009, 2021). "However, a number of large retrospective studies failed to validate an association between BRAF positive tumours and poor prognosis." (PMID 34734568, 2021). "BRAF inhibitors together with MEK inhibitors could induce pyroptosis in melanoma with a higher HMGB1, more tumor-associated T cells, and less dendritic cell infiltration, while GSDME deficiency would reverse the anti-tumor immunity." (PMID 34298833, 2021). "The results indicate that the absence of a BRAF V600 mutation and PD-L1 tumor expression are associated with a favorable response to DPCP, and qualitative assessment of CD8+ TILs may be useful for predicting the clinical outcome with DPCP." (PMID 32542563, 2021). "Notably, in accordance with previous evidence, primary tumor location did not appear to have a prognostic value in BRAF-mutated mCRC." (PMID 33925278, 2021). "Our case presented a microsatellite stable (MSS) tumor without BRAF activating mutations." (PMID 33731191, 2021). "The same analysis revealed significantly lower expression of RAC1B in MSI tumours and/or tumours carrying mutations in BRAF as hypothesised by the negative correlation with CMS1." (PMID 33879799, 2021). "Furthermore, it would limit the ability to assess if depletion of tumor associated proinflammatory macrophages and cross-priming CD103+ dendritic cells which we have previously observed with BRAF-MEK-CDK4/6i treatment would limit the efficacy of concurrent ACT treatment." (PMID 34944961, 2021). "Furthermore, the introduction of a first immunocompromised version of the AlbuMus allows accurate anti-tumour investigations of an anti-EGFR x anti-CD3 bispecific albumin fusion in BRAF-mutated tumours non-respondent to standard anti-EGFR monoclonal therapies." (PMID 33686177, 2021).
tumor (continued). "Likewise, the expression of the downstream target of the BRAF oncogene PD-L1 may decrease at the tumor cell surface." (PMID 33391536, 2021). "If this phenomenon is true for paediatric cancers, it could explain why liquid biopsies are not popular in pLGGs, as the circulating tumour DNA concentration in plasma could be too low for detecting BRAF V600E mutations." (PMID 33557011, 2021). "On the other hand, the presence of a MAPK pathway alteration, such as FGFR1 or BRAF mutations, may open up additional possibilities of targeted therapies, independent of the tumor classification." (PMID 33433639, 2021). "To study the tumor cell-intrinsic differences in response to commonly used therapies between dMMR and pMMR CRC, we generated a PDO cohort of six dMMR and six pMMR CRC-derived PDOs with annotated primary tumor location (sidedness) and BRAF- and KRAS-mutational status." (PMID 34771595, 2021). "Thus, the concordance of cfDNA and tumor DNA for BRAF V600Mx was 76%." (PMID 32284750, 2020). "Moreover, it should be noted that the influence of tumor BRAF mutation status was not investigated in the PREMIUM study whereas BRAF mutations negatively impact the treatment outcomes in mCRC." (PMID 33347495, 2020). "Therefore, targeting tumor stroma might be a potential strategy to prevent BRAF inhibitor resistance." (PMID 32373541, 2020). "However, novel compounds targeting tumor‐specific molecular changes, such as EGFR and BRAF mutations, and ALK fusions, or immunomodulatory agents activating anti‐tumor immune responses, are challenging this paradigm, and some of these drugs show intracerebral efficacy." (PMID 32858763, 2020). "In addition to KRAS, other components like BRAF, MEK, and MAPK1 are also involved and mutation in one of them leads to a constitutive activation of MAPK/ERK signaling pathway that ultimately results in neoplasm." (PMID 32612457, 2020). "Considering the small number of patients, the association between the expression of SK1 and the tumor stage, the mutation status of BRAF and NRAS, as well as immune responses could not be performed due to weak statistical power in this retrospective study." (PMID 31974367, 2020). "Based on results obtained in PTEN-loss/BRAF-mut melanoma, the authors demonstrated that a combination of OX40 receptor agonists and PI3K inhibitors successfully improves tumor immune response by promoting the proliferation and cytotoxicity of CD8+ T cells at the tumor site." (PMID 32727102, 2020). "Due to the small number of patients analyzed and the intensive treatment regimens applied in all patients, it is impossible to determine whether the unfavorable tumor control after DpR is specific for BRAF-MT mCRC in general or for BRAF-MT mCRC treated with FOLFOXIRI regimens." (PMID 32449003, 2020). "Targeted therapies directed at tumour cells harbouring epidermal growth factor receptor (EGFR) gene mutations, anaplastic lymphoma kinase (ALK) gene rearrangements, ROS proto-oncogene 1 (ROS1) gene fusions, and B-Raf proto-oncogene (BRAF) gene mutations have produced impressive results." (PMID 32907572, 2020). "The oncogenic potential of Ψ-BRAF was underlined by the need to have no supplementary engineered mutations to force the onset of the phenotype and by the possibility to completely regress the tumor upon Dox withdrawal." (PMID 32605220, 2020). "Similar analyses from the BEACON-trial investigating a targeted combination therapy with BRAF-, MEK-, and EGFR inhibition in BRAF-MT mCRC patients could clarify to which extent tumor dynamics observed in the VOLFI trial are also evident with targeted tumor therapy." (PMID 32449003, 2020).
tumor (continued). "Upon progression, BRAF inhibitor‐related, positive immunoregulatory effects are cleared, suggesting that BRAF inhibitor resistance is associated with an immunosuppressed tumor microenvironment, potentially contributing to a lack of response to subsequent anti‐PD‐1 therapy." (PMID 32330348, 2020). "In case 1, in the absence of tumor tissue biopsy, the presence of a BRAF mutation in cfDNA might have been interpreted as an underlying resistance mechanism to the EGFR inhibition." (PMID 33207619, 2020). "Also, recent meta-analyses demonstrated that patients with a BRAF V600E–mutated tumor do not benefit from the addition of anti-EGFR mAbs." (PMID 31705176, 2020). "The BRAF mutation is also a tumor agnostic genetic alteration and therefore it could become targetable, regardless of the tumor origin." (PMID 33152998, 2020). "Multivariate Cox regression analysis suggested that AHNAK2 could become an independent predictor after adjusting for other parameters, including age, gender, American Joint Committee on Cancer (AJCC) stage, BRAF mutations, RAS mutations and tumor mutation burden (TMB) (PFS as the ending indicator)." (PMID 32966238, 2020). "The BRAF c.1799 T > A (V600E) point mutation had the greatest indicative power of all variants; actually this mutation was present in 13 tumors and never occurred in tumor-free tissues." (PMID 31758407, 2020). "Specific germline polymorphisms or composite haplotypes, in conjunction with tumor features (e.g., sidedness) and molecular profile (e.g., RAS, BRAF, HER2, MSI status, CMS subtype) may serve to inform the selection of mCRC patients to treat with cetuximab and other targeted or immune therapies." (PMID 33065994, 2020). "Tumor A_1 showed no additional alterations except for a BRAF (p.V600E) mutation." (PMID 32758285, 2020). "This comparable HR of the BRAF V600E mutation for recurrences remained non-significant (pooled HR 1.16, 95% CI 0.78–1.71) after adjustment for potential confounders, including age, sex, and tumor size." (PMID 32722429, 2020). "BRAF c.1799 T > A (V600E) is considered the most prevalent genetic alteration in PTC, and it has also been associated with more aggressive tumor behavior, such as extrathyroidal extension, lymph node involvement, resistance to radioactive iodine and tumor recurrence." (PMID 31758407, 2020). "Key mechanisms of acquired resistance to combination BRAF inhibitor and MEK inhibitor therapy include mutations in MEK and NRAS25; however, it is unknown whether cells expressing these mutations are pre-existing in the tumor or the mutations occur de novo." (PMID 32504051, 2020). "One CNS-specific obstacle to BRAF targeted therapy may be the blood-brain or blood-tumor barrier." (PMID 33042847, 2020). "However, visual asymmetry was observed in the BRAF prevalence analyses for both tumor sides with more studies scattered about the left side of the mean, indicating that the estimate may be skewed toward zero (data not shown)." (PMID 31856410, 2020). "Male gender, no tumour response at first evaluation and BRAF mutation are associated with a short CFI, and may be considered for maintenance chemotherapy after IC." (PMID 32015513, 2020). "Since we observed that pre-existing NGFRhi tumor cells could expand selectively on T cell pressure, and because we observed that those expanded fractions are resistant to BRAF + MEKi, we then tested whether this cross-resistance phenomenon also occurred in vivo." (PMID 32770055, 2020). "Thus BRAF inhibition controls tumor progression while also altering the tumor site toward a “small” TME, suggesting combination with other immune interventions may be highly effective." (PMID 33597954, 2020). "On the other hand, a positive result from a sensitive molecular technique may reflect a minor BRAF-mutated subclone in a predominantly wild-type tumor, and this is thus not clinically relevant in terms of response to targeted therapy." (PMID 32695793, 2020).
tumor (continued). "Our studies suggest that mutation of FBXW7 may confer resistance of tumor cells to BET inhibitors JQ1 and OTX-015 and at least some mutations within the WD40 domain of FBXW7 provide resistance because of their inability to target BRAF for degradation." (PMID 32907612, 2020). "Although with negative BRAF mutations, we could not exclude that poor tumor behavior is associated with the coexistence of TERT promoter mutation, which was not tested in this study." (PMID 31295281, 2019). "Analyses did not reveal BRAF mutation and the PD-L1 expression in tumour cells was below 1%." (PMID 32123804, 2019). "Furthermore, because signals from the tumour microenvironment can influence MAPK signalling the dynamic regulation of MITF downstream of BRAF might explain at least in part the significant heterogeneity in MITF expression that is observed in human tumours." (PMID 30277012, 2019). "However, it cannot be excluded that additional mutations in the tumor, like KRAS or BRAF, might influence FAM83A and/or B expression." (PMID 31083571, 2019). "However, certain other research questions, e.g. characterizing very small populations such as BRAF-mutant mCRC patients by variables including primary tumor site, may require a side of colon variable with greater completeness of specific side of colon data." (PMID 31426736, 2019). "No additional BRAF mutations over tumor tissue testing were identified in baseline ctDNA." (PMID 31350822, 2019). "Taken together, the phenotypic analysis of tumor-infiltrating leukocytes (TILs) might be important not only to evaluate the efficacy of immune therapy, but also to understand the mechanisms to overcome the acquisition of resistance to BRAF inhibitors." (PMID 31514399, 2019). "Interestingly, the three most common BRAF fusions are not evenly distributed and are strongly associated with infratentorial tumor location and younger age of onset." (PMID 31181803, 2019). "We also found a negative association between distant metastases and mutated BRAF tumours." (PMID 31093278, 2019). "Several studies suggest that detection of a wild type BRAF (B-Raf proto-oncogene) in the primary tumour may not necessarily reflect the BRAF mutation status of metastases." (PMID 30934988, 2019). "No BRAF or KRAS mutation was detected in cfDNA from patients with wild‐type tumor tissue." (PMID 31134762, 2019). "Interestingly, overexpression of HER2 and HER3 may provide a mechanism of RAI-R tumor escape for BRAF mutant cells treated with the BRAF inhibitor vemurafenib." (PMID 31533238, 2019). "Considering that BRAF mutation was detected in more than half of our PTC and most of the patients present indolent disease, other molecular mechanisms might be responsible for a more aggressive tumor phenotype." (PMID 30884810, 2019). "Most of the tumor tissues that expressed PD-L1 were BRAF V600E mutation negative (P = 0.002)." (PMID 31664962, 2019). "We examined whether high PD-L1 expression, tumor mutational burden (TMB), and presence of targetable mutations (EGFR, BRAF, ERBB2, RET or ALK translocations, ROS1 rearrangements) occur at different frequencies in tumors from black patients compared to non-black patients." (PMID 31645901, 2019).